BDNF (brain derived neurotrophic factor)
Diseases named in the same sentence as BDNF in open-access papers (continued):
Sharing a sentence is not in itself a finding about the gene and the disease.
Obesity (continued). "Genetic variations in FTO, BDNF, and MC4R genes, related to increased risk of weight gain, have been reported to be linked to elevated BMI and obesity risk in large-scale genome-wide association studies." (PMID 40423790, 2025). "A randomized controlled study conducted on a population with obesity revealed that the levels of circulating BDNF were higher in women at baseline." (PMID 39789839, 2025). "The selective deletion of BDNF in the hypothalamus of adult mice resulted in increased food intake and obesity." (PMID 39857710, 2025). "In contrast, circulating BDNF levels increase after exercise training in people with obesity and T2D and correlate positively with muscle strength in lower limbs." (PMID 40171198, 2025). "Another interesting study in muscle-specific BDNF knockout mice showed that ingesting a high-fat diet exacerbated the development of obesity, insulin resistance, intramyocellular lipid deposition and mitochondrial dysfunction." (PMID 39857710, 2025). "A comprehensive study analyzing the association between BMI and approximately 2.8 million SNPs in over 123,865 individuals identified a significant correlation between obesity and a 32-locus, notably implicating rs10767664 proximal to the BDNF gene." (PMID 40697550, 2025). "Three of the loci harbor genes implicated in severe and early-onset obesity – ADCY3, BDNF, and MC4R4." (PMID 40216759, 2025). "Specifically, it highlights that genetic variants such as BDNF rs6265 and FTO rs1421085 are primarily associated with obesity risk in individuals with low energy intake." (PMID 40002356, 2025). "Studies on neuroplasticity-related proteins, including BDNF, have suggested that inflammation and oxidative stress in obesity promote their upregulation." (PMID 40004753, 2025). "The effect is bidirectional: obesity has been shown to reduce BDNF levels, and SCZ, by increasing IL-6 levels, also contributes to its reduction." (PMID 41007867, 2025). "Circulating BDNF levels have been studied as potential biomarkers for obesity, with some studies reporting decreased levels in individuals with obesity, although findings are inconsistent." (PMID 41082226, 2025). "Plasma BDNF levels decline with age and are further reduced in conditions such as neurodegenerative diseases, obesity, type 2 diabetes, and sarcopenia." (PMID 41441428, 2025). "Dysregulation through compromised BDNF signaling within the hypothalamic neural circuits, due to a lack of leptin‐induced BDNF mRNA translation can lead to leptin resistance, resulting in obesity." (PMID 39853792, 2025). "Understanding the exercise-BDNF relationship in adolescents has significant clinical and public health implications, particularly given the rising prevalence of sedentary behavior, obesity, and mental health concerns in this population." (PMID 40863762, 2025). "This suggests that genetic variants, such as BDNF rs6265, FTO rs1421085, and SEC16B rs506589, are more likely to predispose individuals to obesity when their energy intake is below the EER." (PMID 40002356, 2025). "A recent study revealed that a single exercise session can restore BDNF signaling in obese mice, suggesting intact mechanisms for inducing BDNF signaling in obesity." (PMID 38988101, 2024). "It has been implicated in appetite as central administration reduces food intake (~94%) and body weight (~32%) in rodents, and BDNF knockout mice develop hyperphagia and obesity." (PMID 39187396, 2024). "Recognizing this limitation is essential for interpreting our findings and emphasizing the need for more focused investigations into the specific effects of different exercise programs on circulating BDNF in the context of obesity." (PMID 38785805, 2024). "Previous reports demonstrated that BDNF knockout mice exhibited overeating and obesity phenotypes remarkably." (PMID 38672461, 2024). "Consistently, genetically engineered rodents with CNS BDNF knockdown develop hyperphagia and obesity." (PMID 39655343, 2024).
Obesity (continued). "Regarding the studies analyzed, high-intensity exercise protocols were commonly used in patients with obesity, resulting in elevated circulating BDNF levels." (PMID 38785805, 2024). "These pathways illustrate the communication between peripheral fat pads and the hypothalamus, clarifying the roles of both central and peripheral BDNF in the relationship between obesity and hypertension." (PMID 39655343, 2024). "The present meta-analysis represents a pioneering effort in investigating the impact of acute and regular physical activity on circulating BDNF levels, focusing exclusively on individuals with obesity." (PMID 38785805, 2024). "In conclusion, these results unveil a previously unrecognized PVHSH2B1→DRN neurocircuit through which SH2B1 defends against obesity by enhancing BDNF/TrkB signaling." (PMID 38885417, 2024). "Several of the high-scoring genes (score ≥ 11) are known to be implicated in obesity (such as DGKI [score: 22.8], MC4R [19.6], BDNF [19.6], MTOR [16.8], SH2B1 [14.8], GIPR [14.3], AKT3 [11.6], and LEPR [11.6])." (PMID 38754426, 2024). "This review delves into the complex mechanisms involving BDNF and estrogen, especially in the context of hypertension and obesity, particularly among postmenopausal women." (PMID 39655343, 2024). "While childhood obesity remains a significant health concern, included studies in our meta-analysis concentrates on exploring circulating BDNF responses to exercise in especially adults with obesity." (PMID 38785805, 2024). "Research is needed to confirm our findings and determine whether carriers of the BDNF Val66Met homozygous Val (G/G) alleles may be at risk of diminished HRQoL, information that can influence interventions in a high‐risk population of inactive youth with obesity." (PMID 38997217, 2024). "The aim of this systematic review with meta-analysis was to understand the acute (short-term) and regular (long-term) effects of physical exercise on circulating BDNF levels in patients with obesity." (PMID 38785805, 2024). "Central BDNF plays a crucial role in modulating how target tissues respond to these stimuli, influencing the pathogenesis of hypertension, mitigating obesity, and protecting neurons from aging." (PMID 39655343, 2024). "Since BDNF has anti-obesity and anti-diabetic actions, this explains the role of gut microbiota in the pathobiology of obesity, diabetes mellitus, and metabolic syndrome." (PMID 38641607, 2024). "Lastly, BDNF’s pivotal role in brain development, cognition, and mood regulation is extensively documented, particularly in adults with obesity." (PMID 38785805, 2024). "BDNF also regulates metabolism and energy balance, with emerging studies suggesting that BDNF has a key role in controlling glucose homeostasis and body weight, with action also to metabolic disruptions such as diabetes and obesity." (PMID 39596862, 2024). "This investigation underscores the potential utility of both acute and regular exercise regimens in positively modulating circulating BDNF levels in the context of obesity." (PMID 38785805, 2024). "Acute exercise led to a significant increase in the concentration of circulating BDNF patients with obesity compared to the control group." (PMID 38785805, 2024). "Future research should concentrate on understanding how the body adapts to exercise and exploring innovative approaches to enhance circulating BDNF regulation through physical activity in individuals with obesity." (PMID 38785805, 2024). "We previously found that BDNF heterozygous mice exhibited hepatic steatosis, one of the most frequent symptoms observed in obesity and that liver lesions of MASH coincide with increased levels of food intake, body weight, serum glucose and insulin." (PMID 38672461, 2024). "Despite the expanding body of evidence, the precise mechanisms by which circulating BDNF exerts its neuroprotective effects in the context of obesity remain partially understood." (PMID 38785805, 2024).
Obesity (continued). "Suppression of BDNF mRNA in the ARC leads to severe hyperphagic obesity, accompanied by decreased axonal projections from the ARC to the PVN, further demonstrating the importance of BDNF signaling in central metabolic regulation." (PMID 39203753, 2024). "The meta-analysis of 16 studies with 23 trials revealed an increase in BDNF levels after a single session of exercise in individuals with obesity." (PMID 38785805, 2024). "Animal models, in particular homozygous knock-in BDNF met/met mice, showed a phenotype characterized by hyperphagia, obesity, and altered inflammatory profiles in addition to reduced hypothalamic BDNF expression." (PMID 39203753, 2024). "The meta-analysis revealed a statistically significant increase in circulating BDNF levels in individuals with obesity compared to controls (Effect Size, ES: 1.25, large effect, p < 0.05)." (PMID 38785805, 2024). "The link between obesity and altered BDNF signaling underscores the importance of understanding how physical exercise, a primary intervention for obesity management, affects circulating BDNF levels." (PMID 38785805, 2024). "Based on the studies mentioned (3 studies, 6 trials), regardless of the type of exercise, it has been shown that circulating BDNF levels increase in patients with obesity after both acute moderate (1 trial) and high-intensity exercises (5 trials)." (PMID 38785805, 2024). "In a mouse model of diet-induced obesity, EE effectively prevents weight gain and promotes adipose browning by elevating hypothalamic brain-derived neurotrophic factor (BDNF) levels." (PMID 39000013, 2024). "The meta-analysis reveals that acute exercise induces a noteworthy elevation in circulating BDNF levels among individuals with obesity when compared with the control group." (PMID 38785805, 2024). "Physiologically, BDNF is recognized as an anti-obesity molecule, while estrogens promote lipolysis and help prevent obesity." (PMID 39655343, 2024). "BDNF and estrogens work cooperatively to prevent obesity by favoring lipolysis, and counteractively regulate blood pressure to adapt to the environment." (PMID 39655343, 2024). "Obesity relates to increased estrogen, who modulates synaptic plasticity and brain derived neurotrophic factor expression in the hippocampus, contributing to neuroprotection, and such effect was only observed in female, but not in male." (PMID 38520024, 2024). "Both BDNF and estrogens play critical roles in the development of hypertension and obesity, particularly in the postmenopausal context." (PMID 39655343, 2024). "Collectively, these results suggest that PVHSH2B1 neuron‐intrinsic SH2B1 protects against energy imbalance and obesity at least in part by enhancing BDNF/TrkB pathways in the PVH." (PMID 38885417, 2024). "This review examines recent advances in understanding the interaction between BDNF and estrogen in the context of hypertension and obesity." (PMID 39655343, 2024). "Future studies with rigorous study design should be guaranteed to verify the gender roles in BDNF responses to exercise interventions in obesity." (PMID 38618555, 2024). "Such a nuanced approach promises to enhance our understanding of BDNF dynamics across the lifespan and guide targeted strategies for managing obesity and promoting brain health." (PMID 38785805, 2024). "Dysregulation of BDNF, in particular can lead to impaired activation of tyrosine kinase receptor β (TrkB), resulting in obesity, insatiable appetite, and reduced energy expenditure." (PMID 38540381, 2024). "Physical exercise offers health benefits, including improved circulating BDNF levels and cognitive function, but the specific impacts of acute versus regular exercise on circulating BDNF levels in obesity are unclear." (PMID 38785805, 2024). "A reduced concentration of BDNF was observed in the blood of patients suffering from mental diseases, such as depression, schizophrenia or dementia, as well as obesity, type 2 diabetes or coronary artery disease." (PMID 39770947, 2024).
Obesity (continued). "The relationship between BDNF and some metabolic disorders such as obesity and metabolic syndrome have additionally been addressed." (PMID 37596403, 2023). "It has been shown previously that hyperphagia, obesity, and metabolic imbalances are related to BDNF deletion in both knockout mice and humans." (PMID 37072879, 2023). "Several studies have reported low BDNF concentrations in adult patients with obesity, type 2 diabetes mellitus and metabolic syndrome (MetS)." (PMID 37548699, 2023). "Patients carrying monogenic mutations in either BDNF or NTRK2 (encoding TRKB) experience severe hyperphagic obesity." (PMID 37956053, 2023). "The results of the present study indicate the distinct effect of obesity and sex on BDNF concentrations during adolescence and provide hints for the development of more personalized interventions and ways of prevention." (PMID 37548699, 2023). "Nevertheless, the relationship between BDNF and obesity seems to be complex, and many factors are considered to be involved in this relationship, including biological, environmental, behavioral, and genetic factors." (PMID 37007871, 2023). "Scarce data exist about the concentrations of BDNF in children and adolescents in relation with obesity and metabolic syndrome (MetS)." (PMID 37548699, 2023). "The sample was further divided into four categories by sex and BMI status, with normal-BMI females exhibiting significantly lower BDNF concentrations than females and males with obesity(p = 0.005)." (PMID 37548699, 2023). "Our findings suggest that a reduction in BDNF/Trk-B signaling contributes to changes in lipid metabolism that lead to hepatic steatosis and obesity, which are symptoms of the metabolic syndrome." (PMID 38152248, 2023). "Patients with obesity reported a significant positive correlation between visual food cue-reactivity and plasma BDNF levels." (PMID 38136166, 2023). "BDNF signaling also contributes to the development of the metabolic syndrome and obesity under a circumstance with chronic positive energy balance." (PMID 36334250, 2023). "Serum BDNF concentrations differed significantly (p < 0.001) between participants with obesity (mean ± SD; 24,276 ± 5,425 pg/mL) and those with normal BMI (mean ± SD; 18,009 ± 7,495 pg/mL)." (PMID 37548699, 2023). "Studies have shown decreased levels of NGF and BDNF in conditions like metabolic syndrome, acute coronary syndromes, and obesity, suggesting their potential involvement in the development of atherosclerosis and metabolic disorders." (PMID 38026693, 2023). "Increased serum BDNF concentrations were observed in MetS adolescents with obesity when compared with normal-BMI adolescents (p < 0.001)." (PMID 37548699, 2023). "Some studies suggest lower serum BDNF levels in obesity compared to normal‐weight individuals, indicating a potential risk for obesity in individuals with lower BDNF levels." (PMID 37822121, 2023). "On the other hand, deletion or interruption of BDNF-TrkB signaling results in significant hyperphagocytosis and severe obesity in mice." (PMID 37598204, 2023). "Normal-BMI females had significantly lower BDNF concentrations, when compared with females and males with obesity." (PMID 37548699, 2023). "Nesfatin-1, neuregulin 4, myonectin, irisin, and brain-derived neurotrophic factor (BDNF) all seem to have protective effects against obesity." (PMID 38136166, 2023). "Aerobic exercises reduce the TGs in adults who are overweight or have obesity, and exercising and dietary control have been shown to reduce BDNF in women with obesity." (PMID 37075032, 2023). "The role of BDNF-producing neurons in human obesity disorders and how the activity of these cells is regulated remained poorly studied." (PMID 37956053, 2023). "Adolescents with MetS and obesity presented with increased BDNF concentrations when compared with their normal-BMI counterparts." (PMID 37548699, 2023).
Obesity (continued). "Adults with obesity have low BDNF concentrations in serum, while adolescents with obesity in this study demonstrated an increase." (PMID 37548699, 2023). "In the present study obesity appeared as a major factor for increased serum BDNF concentrations in adolescents with MetS (vs. normal BMI), with a higher impact on BDNF concentrations in females than males." (PMID 37548699, 2023). "Individuals with obesity, attention deficit hyperactivity disorder, and autism spectrum disorder, for example, have been reported to have altered levels of BDNF compared to neurotypical ones." (PMID 37786524, 2023). "In turn, in neonates, a relationship between BDNF levels and cigarette and alcohol consumption during pregnancy, as well as obesity in pregnant women, has been demonstrated." (PMID 36831706, 2023). "In previous studies, researchers studied the effect of excessive Zn and showed that 60 ppm of Zn aggravated obesity-induced deficits in hippocampal synaptic plasticity and neurogenesis by decreasing synaptic markers and BDNF levels." (PMID 36977735, 2023). "Animal studies have demonstrated that maternal obesity leads to deficits in spatial learning and memory in the offspring, reducing the BDNF protein levels in the hippocampus." (PMID 38034827, 2023). "They found a positive relationship between BDNF and obesity or type 2 diabetes development in humans due to its role in eating behavior and energy homeostasis." (PMID 37072879, 2023). "This was a case-control study, assessing BDNF concentrations between adolescents with MetS (with obesity vs." (PMID 37548699, 2023). "BDNF-focused interventions are currently under development for obesity, diabetes mellitus, and neurological disorders." (PMID 37548699, 2023). "In patients with WAGR syndrome in which the mutation had affected the BDNF gene, 100% of patients were obese, whereas only 20% of patients with WAGR syndrome with intact BDNF alleles developed obesity." (PMID 36831706, 2023). "The three-SNP model included brain-derived neurotrophic factor (BDNF)_rs6265, fat-mass- and obesity-associated protein (FTO)_rs1421085, and SEC16B_rs509325." (PMID 36839421, 2023). "Our evidence suggests that BDNF-producing neurons are involved in SMS pathogenesis and that enhancing BDNF-TRKB signalling should be explored as a future therapeutic avenue for obesity and metabolic conditions associated with reduced neurotrophin signalling." (PMID 37956053, 2023). "Further studies to elucidate the exact role of BDNF in the physiopathology of obesity in prepubertal children were also recommended." (PMID 37638319, 2023). "Among female participants, mean BDNF concentration was significantly higher (p = 0.001) in those with obesity (mean ± SD; 24,235 ± 4,144 pg/mL) than females with normal-BMI (mean ± SD; 15,795 ± 7,721 pg/mL)." (PMID 37548699, 2023). "We examined the body weights of these lines at 5 months of age, since the BDNF heterozygous (Bdnf+/−) mice begin to exhibit obesity at this age." (PMID 37238691, 2023). "Our previous cancer and obesity studies identified BDNF as the key brain mediator for improved metabolic and immunity outcomes following EE, and our EE-BTBR study found that Bdnf and Ntrk2 were upregulated following EE." (PMID 36893171, 2023). "In this study, we examined serum BDNF concentrations between adolescents with MetS (with normal-BMI vs. obesity." (PMID 37548699, 2023). "Further, multiple topics, including age, obesity, chronic stress, and antibiotic treatment, concerning the involvement of the microbiota in neurogenesis and BDNF expression were found." (PMID 36555576, 2022). "Among the differentially expressed genes were neuroplastin (nptn), brain-derived neurotrophic factor (BDNF) and neuronal growth regulator 1 (Negr1)—genes associated with cognition, neuronal growth, plasticity and obesity." (PMID 35953488, 2022).